IL5RA (interleukin 5 receptor subunit alpha)
Description:
Cell surface receptor that plays an important role in the survival, differentiation, and chemotaxis of eosinophils. Acts by forming a heterodimeric receptor with CSF2RB subunit and subsequently binding to interleukin-5. In unstimulated conditions, interacts constitutively with JAK2. Heterodimeric receptor activation leads to JAK2 stimulation and subsequent activation of the JAK-STAT pathway.
Synonyms: CD125; IL5R; CDw125; HSIL5R3
Tractability: Antibody: an approved drug acts on it; its Gene Ontology location is reachable by antibodies, with high confidence; UniProt predicts a signal peptide or a membrane-spanning region.
Target class: Membrane receptor
Gene: Protein-coding gene on chromosome 3 (3,066,324 to 3,126,613, reverse strand). Ensembl gene ENSG00000091181.
Subcellular location: Membrane
Pathways (Reactome):
Immune System: Interleukin receptor SHC signaling; Interleukin-3, Interleukin-5 and GM-CSF signaling
Signal Transduction: RAF/MAP kinase cascade
Gene Ontology:
Molecular function: interleukin-5 receptor activity; protein binding; cytokine binding; cytokine receptor activity
Biological process: cell surface receptor signaling pathway via JAK-STAT; interleukin-5-mediated signaling pathway; cytokine-mediated signaling pathway; positive regulation of cell population proliferation; positive regulation of leukocyte proliferation; signal transduction
Cellular component: external side of plasma membrane; extracellular region; interleukin-5 receptor complex; membrane; plasma membrane; receptor complex
Genetic constraint (gnomAD): Loss-of-function variants: 28 observed, 28.37 expected, observed/expected ratio (o/e) 0.99, 90% interval 0.73 to 1.35. The upper end of that interval is the gene's LOEUF score, 1.35, which puts it in group 5 of 6, group 1 being the genes least tolerant of losing a copy. Missense variants: 320 observed, 279.58 expected, observed/expected ratio (o/e) 1.14, 90% interval 1.04 to 1.26. Synonymous variants: 112 observed, 98.16 expected, observed/expected ratio (o/e) 1.14, 90% interval 0.98 to 1.34.
Homologues: Orthologues: macaque IL5RA (94% identical), chimpanzee IL5RA (93% identical), pig IL5RA (77% identical), dog IL5RA (76% identical), guinea pig IL5RA (71% identical), mouse Il5ra (68% identical), rat Il5ra (66% identical). Paralogues in human: IL12RB1 (14% identical), IL6ST (13% identical), IL31RA (13% identical), LEPR (11% identical), OSMR (11% identical), CSF3R (10% identical), LIFR (10% identical), IL12RB2 (10% identical), IL27RA (10% identical), IL23R (8% identical), PRLR (8% identical), CRLF1 (7% identical), and 11 more.
Diseases named in the same sentence as IL5RA in open-access papers:
IL5RA is named in the same sentence as 101 diseases in open-access papers, as found by Europe PMC text mining. Sharing a sentence is not in itself a finding about the gene and the disease. The quoted sentences say what the papers report.
asthma (117 papers, 2016 to 2026). "It binds to IL-5 and prevents IL-5 from interacting with IL-5Rα on eosinophils, which reduces eosinophil count and risk of asthma exacerbations." (PMID 38493955, 2024). "Two antibodies against IL-5 and one against IL-5Rα are now approved treatments for severe asthma associated with persistent eosinophilia, in addition to glucocorticoid therapy, reducing annualized exacerbation rates and moderately improving lung function." (PMID 40047886, 2024). "Hypermethylation in GATA3 CpG loci was associated with a decreased risk of asthma at birth, and hypomethylation of IL-13 and interleukin 5 receptor subunit alpha (IL5RA) was associated with an increased risk of asthma in teenagers." (PMID 33732246, 2021). "In general, there was an association between asthma severity and increased levels of IL5RA expression." (PMID 33644088, 2020). "We choose several genes associated with Eos asthma, including Il5RA, GATA3, SATAT5, and SOCS, to identify co-expressed lncRNAs." (PMID 30941157, 2019). "Both current asthma at 16.5 years and ever wheeze at 16.5 years were negatively associated with methylation levels at IL5RA, a gene encoding alpha subunit of the interleukin-5 (IL5) receptor." (PMID 29046734, 2017). "Moreover, polymorphisms in IL5RA account as a genetic risk factors for asthma development, especially in atopic populations." (PMID 35344303, 2022). "Benralizumab is a monoclonal antibody targeting the alpha subunit of the interleukin-5 receptor (IL-5Rα) approved for the treatment of severe and uncontrolled asthma in patients aged ≥ 12 years." (PMID 40003269, 2025). "The ABRA trial tested benralizumab (anti-IL5Rα) during active eosinophilic exacerbations of asthma/COPD and evidenced a reduced failure rate (against prednisolone) and reduced hospital readmissions." (PMID 40364184, 2025). "This systematic review shows that approximately half of patients with ATS/ERS-defined severe asthma worldwide meet eligibility criteria for at least 1 biologic therapy targeting IgE, IL-5/IL-5Rα, or IL-4Rα." (PMID 41488544, 2025). "The relative specificity of this receptor for eosinophils among circulating granulocytes suggested monoclonal antibodies against IL-5 and IL-5Rα as a strategy to mitigate eosinophil-driven pathology in asthma." (PMID 40047886, 2024). "Benralizumab (BRZ), a humanized monoclonal antibody, targets the interleukin-5 receptor alpha (IL-5Rα) on eosinophils, thereby reducing eosinophilic inflammation central to asthma pathogenesis." (PMID 38956390, 2024). "Utilized in the management of asthma, Mepolizumab and Benralizumab, are monoclonal antibodies that target IL-5 and IL-5Rα, respectively." (PMID 38541674, 2024). "IL5RA, targeted by benralizumab in clinical trials for CRSwNP and approved for asthma, is known for its role in eosinophil maturation, but its expression on human B cells is not well established." (PMID 39253973, 2024). "A significant increase in IL5RA expression was observed in CRSwNP patients, especially those with asthma and atopy." (PMID 37509606, 2023). "The hypomethylation of IL5RA gene on airway epithelial cells and eosinophils has shown to be a therapeutic target for asthma." (PMID 38043345, 2023). "In the present study, we retrospectively evaluated the efficacy and safety of these anti-IL-5/IL-5Rα mAbs in 29 Japanese patients with asthma-complicated ABPA." (PMID 37015988, 2023). "Targeting IL-5 or IL-5Rα, the main mediators of eosinophilic inflammation, through monoclonal antibodies can reduce eosinophilia in severe asthma patients with uncontrolled symptoms." (PMID 38259298, 2023). "The IL5RA gene also showed an important link with the pathogenesis of asthma in a multi-omics approach." (PMID 38043345, 2023). "Interleukin 5 receptor subunit alpha (IL-5Rα) involves the activation, maintenance, and survival of eosinophils, which are highly tied to chronic inflammatory processes of the airways, like asthma or CRSwNP." (PMID 37509606, 2023).
asthma (continued). "Hypomethylation of the IL5RA gene in Airway Epithelial Cells (AECs) and eosinophils has been shown to be a potential therapeutic target for asthma." (PMID 38043345, 2023). "Currently, three classes of monoclonal antibodies targeting type 2 inflammation pathways are available in Italy for the treatment of severe asthma: anti-IgE (Omalizumab), anti-IL-5/anti-IL-5Rα (Mepolizumab and Benralizumab), and anti-IL-4Rα (Dupilumab)." (PMID 37298514, 2023). "Concerning IL5RA, there are plenty of data linking it with asthma in a positively correlating manner." (PMID 35344303, 2022). "Dupilumab, an anti-IL4Rα, was approved in Europe in 2017 for atopic dermatitis and in 2019 for T2 asthma, while the anti-IL-5Rα benralizumab was approved for eosinophilic asthma in 2018." (PMID 35203504, 2022). "These trials have proved the therapeutic efficacy of anti-IL-5 and anti-IL-5Rα antibodies by reducing annual asthma exacerbations." (PMID 36232470, 2022). "Mepolizumab (Nucala) is the first approved monoclonal antibody (mAb) targeting IL-5, blocking the binding of IL-5 to IL-5Rα, which reduces blood eosinophil counts and exacerbations of asthma and improves asthma control." (PMID 36403040, 2022). "To assess the function of IL-5-anchored CCAR-T cells in the murine asthma models, we designed murine variants based on mIL-5-anchored CCAR-T cells or CCAR-Jurkat cells specific for murine IL-5Rα (mIL-5Rα)." (PMID 35973984, 2022). "Mepolizumab and reslizumab, monoclonal anti-IL-5 antibodies, and benralizumab, which targets IL-5Rα, are approved for the treatment of asthma and have shown to improve allergic asthma." (PMID 36389745, 2022). "The biologic drugs currently available (anti-IgE, anti-IL4Rα, anti-IL5, and anti-IL5Rα) for severe asthma are currently undergoing clinical development studies to extend their availability to patients with nasal polyposis." (PMID 35743736, 2022). "While the functional relevance of IL-5Rα+ ILC2 is unclear, these changes were associated with improved asthma control and lung function." (PMID 34630416, 2021). "Mepolizumab and benralizumab are antibody preparations that target IL‐5 and IL‐5Rα and have been used in the treatment of asthma." (PMID 34363652, 2021). "The approved humanized monoclonal antibodies (mAbs) for the treatment of asthma are targeted against IgE (omalizumab), IL-5 (mepolizumab and reslizumab), IL-5 receptor α (IL-5Rα; benralizumab), and IL-4/IL-13 (dupilumab)." (PMID 34572466, 2021). "Following the results obtained in the RNAseq study, we decided to carry out a qPCR validation study to evaluate the performance of the peripheral blood IL5RA expression levels in the diagnosis of asthma." (PMID 33644088, 2020). "First, IL5RA is a plausible etiopathogenic target and a biologic target for the treatment of asthma." (PMID 33644088, 2020). "Patients with intermittent asthma had the lowest expression levels of IL5RA (12.0 ± 13.7), while patients with severe asthma had the highest levels (19.9 ± 20.3; P = 0.056)." (PMID 33644088, 2020). "This study aimed to investigate the expression of IL5RA in patients with several types of asthma and its expression after treatment with benralizumab, a biologic directed against IL-5 receptor subunit alpha." (PMID 33644088, 2020). "The present study aims to investigate the expression of IL5RA in patients with different types of asthma and its role as a possible biomarker of response to treatment with benralizumab." (PMID 33644088, 2020). "Nevertheless, we selected IL5RA by its crucial implication in the immunology of T2-asthma and because benralizumab is directed against this molecule." (PMID 33644088, 2020). "This classification scheme differentiates Th2-high asthma, which is amenable to treatment with anti-IgE, anti-IL-5 or anti-IL-5Rα, and anti-IL-4Rα therapy, from Th2-low asthma." (PMID 32509793, 2020). "Blood eosinophil counts and IL5RA expression levels according to asthma diagnosis, sensitization and severity." (PMID 33644088, 2020).
asthma (continued). "Current biologic treatments for severe asthma target a type 2-driven eosinophilic phenotype by blockade of IgE, IL-4Rα, IL-13, and, importantly, IL-5/IL-5Rα." (PMID 31415658, 2019). "Many of the methylation sites we identified have been associated with asthma including ADAM19, EPX, IL4, IL5RA, and PRG2." (PMID 29692868, 2018). "Specifically, we identified multiple methylation loci in genes previously associated with asthma (ADAM19, EPX, IL4, IL5RA, and PRG2) from genome-wide and epigenome-wide association studies." (PMID 29692868, 2018). "Several of these methylation loci were previously associated with asthma (ADAM19, EPX, IL4, IL5RA, and PRG2)." (PMID 29692868, 2018). "The CpGs mapped to the AP2A2 and IL5RA genes, with a − 2.32 [95% CI − 1.47, − 3.18] and − 2.49 [95% CI − 1.56, − 3.43] difference in percentage methylation in asthma cases respectively." (PMID 29046734, 2017). "Biologic therapies for severe asthma include: anti-immunoglobulin (Ig)E (omalizumab); anti-interleukin (IL)-5 (mepolizumab and reslizumab); anti-IL-5 receptor α (IL-5Rα; benralizumab); and anti-IL-4Rα (dupilumab) and anti-thymic stromal lymphopoietin (tezepelumab)." (PMID 41458996, 2025). "Three therapeutic antibodies have been approved for the treatment of severe asthma with eosinophilic inflammation: mepolizumab and reslizumab (anti-IL-5 antibodies) as well as benralizumab (antibody against the α-chain of the human IL-5 receptor (IL-5Rα))." (PMID 39600395, 2024). "These therapeutic effects of both biologics are of particular importance in the case of steroid-requiring asthma, as controlled studies have shown that the use of anti-IL-5 or anti-IL-5Rα antibodies enables a reduction or complete discontinuation of systemic corticosteroids." (PMID 39600395, 2024). "Main findings of studies comparing BMI on IL-5/IL-5Rα biologic response in severe asthma patients." (PMID 38259298, 2023). "The anti-interleukin-5 (IL-5) monoclonal antibody mepolizumab and the anti-IL-5 receptor α (IL-5Rα) monoclonal antibody benralizumab, both available in Japan, deplete eosinophils by binding to IL-5 or IL-5Rα, thus ameliorating eosinophilic inflammation of the airways in asthma patients." (PMID 37629217, 2023). "At present, treatment with anti-IL5/anti-IL5Rα agents in asthma is initiated according to eosinophil counts and other factors, yet it is possible that a more proximal factor may be an even better predictor of drug response." (PMID 35537820, 2023). "The main finding of this real-world study is that the anti-IL-5Rα biologic treatment determined a significant reduction in asthma exacerbations while improving asthma control and pulmonary function after 6 and 12 months of treatment, in patients with SEA with or without BE." (PMID 37373648, 2023). "Benralizumab, which targets IL5RA, is an approved drug to prevent eosinophilic and severe asthma." (PMID 36793728, 2023). "The epigenetic finding allowed the study and incorporation of the monoclonal antibody Benralizumab21 (Anti-IL-5Ra) in clinical practice, a drug that binds to IL5RA, inducing a reduction in exacerbations and improvement in lung function in patients with severe asthma." (PMID 38043345, 2023). "In this study, we found that asthma participates in the pathogenic mechanism of ACRSwNP by upregulating the expression level of CST1 in the upper airway, and CST1 is associated with the expression level of the type 2 inflammatory cytokine receptor IL5RA." (PMID 36059464, 2022). "However, several studies have described the biomarkers for eosinophilic severe asthma, with peripheral eosinophils being considered the best predictor biomarkers for anti-IL-5 and anti-IL-5Rα therapies." (PMID 33525548, 2021). "Although further studies are required, IL5RA could play a role as a biomarker and pharmacogenetic factor in asthma." (PMID 33644088, 2020). "The more severe the asthma was, the greater the IL5RA levels were." (PMID 33644088, 2020).
asthma (continued). "In accordance, we found the eosinophil marker genes RNASE2 (ribonuclease A family member 2), RNASE3, SIGLEC8 (sialic acid binding Ig-like lectin 8) and IL5RA as well as PRSS33 (serine protease 33) being exclusively expressed in eosinophils in the deconvolved asthma data." (PMID 33076907, 2020). "IL5RA turned out to be one of the genes with the highest differential expression, which is also supported by its relevant role in asthma and its interactions with other immune response effector molecules that were detected in the protein-protein interaction network analysis." (PMID 33644088, 2020). "Type 2‐targeting biologics such as anti‐IgE, anti‐IL4Rα, anti‐IL5, and anti‐IL5Rα have entered the market for selected pheno/endotypes of asthma patients and may soon also become available for CRSwNP patients." (PMID 31090937, 2019). "Two different anti-IL-5 humanized monoclonal antibodies, mepolizumab and reslizumab, have been proven effective in this phenotype of asthma (recently they both came on the market in the United States), as well as an anti-IL-5 receptor alpha (IL5Rα), benralizumab." (PMID 27942351, 2016). "As for IL5RA expression for CRSwNP, the ease and accessibility to obtain the sample from peripheral blood, a minimally invasive method for the patient, outperforms more complex specimens, such as induced sputum in the case of asthma or biopsy in the case of CRSwNP." (PMID 37509606, 2023). "In addition, we observed a progressive increase in the expression of IL5RA levels from intermittent to severe asthma, which could be related to the number of eosinophils to a great extent." (PMID 33644088, 2020). "Moreover, receptors expression is primarily controlled by specific transcription factors, which role in the regulation of eosinophils IL-5Rα transcription is almost unknown in asthma." (PMID 31438916, 2019). "Increasing evidence indicates that biological therapies targeting IgE, IL-5/IL-5Rα, TSLP and IL-33/ST2 can improve not only clinical symptoms but also certain features of airway remodelling in asthma." (PMID 38609094, 2024). "The credibility of results has been verified by selecting four genes (IL5RA, CCR3, IL13RA2, TNFRSF8) which were upregulated in Asthma groups, but downregulated in ART + Asthma groups, according to the log2 (fold change) value." (PMID 36998616, 2023). "Asthma and AR share eight common genes (CLC, EMR4P, IL5RA, FRRS1, HRH4, SLC29A1, SIGLEC8, IL1RL1) that are presumed to describe the link for multimorbidity." (PMID 36825519, 2023). "Therapies targeting mast cell mediators and/or their receptors, including monoclonal antibodies targeting IgE, IL-4/IL-13, IL-5/IL-5Rα, IL-4Rα, TSLP, and IL-33, have been found safe and effective in the treatment of different phenotypes of asthma." (PMID 36430941, 2022). "In asthma neutrophils, the IL5RA (interleukin 5 receptor alpha) gene was identified to be differentially methylated." (PMID 33076907, 2020). "In the EWAS of current asthma at 16.5 years, the two CpGs that remained significant after adjustment for detailed cells mapped to the AP2A2 and IL5RA genes." (PMID 29046734, 2017). "Two studies evaluating 3-year outcomes on anti-IL-5/IL-5Rα therapies found sustained clinical improvements but did not analyze asthma remission." (PMID 40810090, 2025). "The expression level of IL5RA in IL‐5‐activated eosinophils and the levels of IL17RA and CRTH2 in IL‐5 or IL‐17‐activated eosinophils were significantly higher for patients with asthma than for normal individuals." (PMID 39575691, 2024). "In this study, anti-IL-5/IL-5Rα mAbs decreased the frequency of exacerbation, reduced the dose of oral corticosteroids, and improved lung function in patients with ABPA complicated by asthma, even in those refractory to omalizumab." (PMID 37015988, 2023).